OR2A25 (olfactory receptor family 2 subfamily A member 25)
Description:
Odorant receptor.
Synonyms: OR2A25P; OR2A27; OR2A24P
Tractability: Antibody: its Gene Ontology location is reachable by antibodies, with high confidence; UniProt places it where antibodies can reach, with medium confidence; UniProt predicts a signal peptide or a membrane-spanning region.
Gene: Protein-coding gene on chromosome 7 (144,069,811 to 144,075,870, forward strand). Ensembl gene ENSG00000221933.
Subcellular location: Cell membrane
Pathways (Reactome):
Sensory Perception: Expression and translocation of olfactory receptors; Olfactory Signaling Pathway
Gene Ontology:
Molecular function: odorant binding; olfactory receptor activity; G protein-coupled receptor activity
Biological process: detection of chemical stimulus involved in sensory perception of smell; G protein-coupled receptor signaling pathway
Cellular component: membrane; plasma membrane
Genetic constraint (gnomAD): Loss-of-function variants: 0 observed, 0.51 expected, observed/expected ratio (o/e) 0, 90% interval 0 to 1.83. That is too few expected variants to judge how well the gene tolerates losing a copy. Missense variants: 362 observed, 388.12 expected, observed/expected ratio (o/e) 0.93, 90% interval 0.86 to 1.02. Synonymous variants: 162 observed, 154.39 expected, observed/expected ratio (o/e) 1.05, 90% interval 0.92 to 1.2.
Homologues: Orthologues: macaque OR2A25 (93% identical), dog OR2A25 (84% identical), mouse Or2a25 (82% identical), rat Or2a25 (82% identical), guinea pig OR2A25 (80% identical). Paralogues in human: OR2A7 (80% identical), OR2A4 (79% identical), OR2A1 (73% identical), OR2A42 (73% identical), OR2A5 (67% identical), OR2A12 (64% identical), OR2A14 (61% identical), OR2A2 (61% identical), OR1N1 (46% identical), OR1F1 (45% identical), OR10R2 (45% identical), OR7A10 (45% identical), and 116 more.